CD44 (CD44 molecule (IN blood group))
Diseases named in the same sentence as CD44 in open-access papers (continued):
Sharing a sentence is not in itself a finding about the gene and the disease.
tumor (continued). "In breast cancer, apigenin reduced the CD44+/CD24− subpopulation in triple-negative breast CSCs, inducing tumor shrinkage through the downregulation of YAP/TAZ activity." (PMID 36498571, 2022). "The cancer cell stem-like properties were observed in CCT-ESCC cells, as evidenced by the tumor sphere formation and increased expression of CSC biomarkers CD44 and ALDH." (PMID 35252173, 2022). "A study has also implicated the potential to target the cell surface domains of vimentin expressed concomitantly along with the stem cell markers CD44 and CD133 in the tumor-initiating metastatic pancreatic cancer cells derived from lymph nodes." (PMID 35207438, 2022). "Deciphering further molecular aspects of TF regulation in tumor cells, we report here that CD44 and TF coexpress in EMT contexts, and that CD44 acts as a regulator of TF expression supporting procoagulant properties and metastatic seeding." (PMID 35805061, 2022). "An analysis of tumor cells derived from MIA PaCa-2 xenograft mice treated with h4#147D revealed that cell surface expression of CD147 and its binding partners, including CD44 and integrin α3β1/α6β1, was significantly reduced by h4#147D." (PMID 36385956, 2022). "A concomitant decrease in YAP and CD44 expression with RAD18 inhibition was observed, confirming the close correlation between RAD18-induced Hippo-YAP pathway activation and tumor stemness maintenance." (PMID 35413945, 2022). "In terms of grade alone, CBS, CD44, and CHAC1 increased with tumor grade, while HMGCR was decreased." (PMID 35422048, 2022). "C1GalT1-mediated truncation of O-glycans on CD44 inactivates the ERK/NF-κB signaling pathway, resulting in NANOG expression in pancreatic cancer (PC) cells and changes in tumor stem cell characteristics." (PMID 35936713, 2022). "According to our results, the IC50 of Juglone and KPT6566 for CD44+CD133+ tumor-initiating Caco-2 cells and ∆CD44+CD133+ non-tumor-initiating Caco-2 cells was similar." (PMID 35433695, 2022). "A dual staining assay for CD44 and BMI-1 demonstrated that there was an elevated expression of CD44 and BMI-1 in the TRAMP prostates which was considerably downregulated by IP6 treatment across all tumor stages." (PMID 36077751, 2022). "CD44-HBEGF and ANXA1-FRR1, both related to tumor progression, were also exclusive L–R pairs programming CD4, CD8, DC, Gran, and Mφ interactions." (PMID 36008393, 2022). "The IC50 values of KPT6566 for inhibiting cell growth were 5.76 μM for CD44+CD133+ tumor-initiating Caco-2 cells and 5.39 μM for ΔCD44+CD133+ non-tumor-initiating Caco-2 cells, suggesting KPT6566 as another small-molecule compound targeting CD44+CD133+ cells." (PMID 35433695, 2022). "CD44 reduced the sensitivity of tumor cells to CTL by down-regulating the Fas-FasL pathway, leading to tumor escape from CTL killing." (PMID 35942287, 2022). "First, we examined the expression of cancer stem cell marker gene CD44 32, in AOM-DSS-induced tumor model." (PMID 36276637, 2022). "CD44, for example, has been identified as a GSC marker in the tumor periphery and has been suggested to play a role in tumor invasion and migration." (PMID 35954407, 2022). "Neutrophil-derived vesicles have been shown to target tumor cells and inflammatory endothelium through three pairs of interactions including LFA-1/ICAM-1, β1 integrin/VCAM-1, and CD44/L-selectin." (PMID 35874757, 2022). "Mechanistically, SNX5 facilitates the internalization and inhibits the recycling of CD44 in ccRCC cells, thereby inhibiting EMT of ccRCC cells and exerting a tumor suppressor function." (PMID 35024436, 2022). "Tumour-infiltrating CD8+ T cells isolated from CAR(NAP) T-cell-treated mice exhibited an antigen-experienced memory-like (CD62L+, CD44+) phenotype and were degranulated (CD107a+) to a higher degree than those isolated from CAR T-cell-treated mice." (PMID 35379957, 2022). "In the case of nanomaterials containing HA—CD44, LYVE-1, and RHAMM function as selective tumor targets." (PMID 36297526, 2022).
tumor (continued). "LGR5 and CD44 staining in colonic crypt cells and tumor epithelia showed that AOM/DSS induced tumor formation." (PMID 35269806, 2022). "Since conventional markers of cancer stem cells, namely CD133, CD44, KIT, and ALDH1A1, were expressed in all the tumor clusters to a similar extent, we performed cell trajectory analysis." (PMID 35892844, 2022). "CD44 expression in stromal fibroblasts is also important for the transformation of tissue fibroblasts into CAF, which aid tumor survival and local dissemination." (PMID 36148042, 2022). "Our combination was able to induce CD8+ PD1- with high CD44+ and CD69+ expression on both sides of tumor." (PMID 36513720, 2022). "Note that the intracellular homodimerization of CD44 performs as an assistor for HA binding of the ETD, in accordance with the dimer-stimulated tumor exasperation pathway." (PMID 35733341, 2022). "In xenograft tumor tissues after h4#147D treatment, reductions in levels of CD147 and its binding proteins (CD44, integrin α3, integrin α6, and MCT1) were observed." (PMID 36385956, 2022). "The results showed that MHC molecules, MIF-CD74/CXCR4, and MIF-CD74/CD44 in HSIL and lymph nodes were higher than those in tumor tissue." (PMID 35812401, 2022). "Activation of osteopontin receptors expressed on PIN cells, such as CD44 and integrin αv, β1, and β3, subsequently activated Akt and JNK pathways, leading to higher tumor cell proliferation." (PMID 35457063, 2022). "Conversely, CXCR4 overexpression strikingly counteracted the effect of PTX on decreasing Akt phosphorylation and reductions in N-cadherin, vimentin, snail, CD44, CD133, and NANOG protein expression in SKOV3 tumor tissues (*P<0.05)." (PMID 35681259, 2022). "The number of tumor cells with phenotype CD87+CD117+, CD117+Axl+EGF+CD44+, EGF+Axl+, CD117+EGF+, CD276+CD117+, and EGF+Axl− had a tendency to increase." (PMID 36142766, 2022). "We quantified the number of tumor stem cells in CNE-1 using soft agar colony assay and SOX2, CD44 protein expression levels were determined by western blot analysis." (PMID 36403050, 2022). "Upon correlation of CD44 protein expression with patient clinicopathologic characteristics, it was seen that CD44-high patients had significantly advanced American Joint Committee on Cancer (AJCC) stage and T stage tumours." (PMID 35296132, 2022). "Our findings noted that after TAZ knockdown, the apoptosis rate was increased, and CSC markers (CD44, OCT4, and ALDH1A) were downregulated; additionally, the tumor sphere formation ability was decreased significantly." (PMID 36247876, 2022). "Inhibition with PFK158 or genetic knockdown of PFKFB3 showed reduced tumor formation in the CSC xenograft model with reduced expression of phospho-PFKFB3 S461 and total PFKFB3, and cancer stem cell markers including CD133, CD44, Aldh1, Sox2, and ABCG2." (PMID 35804016, 2022). "This multiple-microtissue transcriptome analysis revealed three cancer cell-type clusters in the primary tumor and axillary lymph node metastasis, two of which were cancer stem cell (CSC)-like clusters (CD44/MYC-high, HMGA1-high)." (PMID 35611554, 2022). "Regarding conventional markers of cancer stem cells, CD133, CD44, KIT, and ALDH1A1 exhibited similar expression in all the tumor clusters." (PMID 35892844, 2022). "Considering that CD133 and CD44 are the main markers of tumor-initiating cell subpopulation from SW480 and HCT116 cells, we sorted CD133+/CD44+ SW480 and CD133+/CD44+ HCT116 cells using flow cytometry." (PMID 35470736, 2022). "Immunohistochemistry using various tumor stem cell-specific markers, including acetaldehyde dehydrogenase 1, CD44, CD133, Nestin, NGFR, and SOX9, revealed short spindle-positive cells scattered within the tumor, suggesting the involvement of tumor stem cells." (PMID 36187098, 2022).
tumor (continued). "In the present study, we developed chitosan/hyaluronan nanoparticles (CS/HY NPs) for tumor targeting with vinblastine sulfate (VBL), that can be directed to the CD44 transmembrane receptor, over-expressed in cancer cells." (PMID 35631528, 2022). "In tumor tissue, the malignant epithelial cells not only produced growth factors such as HB-EGF, but also expressed CD44 and CD9 receptors to receive growth signaling, further promoting the tumor progression." (PMID 36172359, 2022). "To validate expression levels of the CCNB1/CDC42/MAPK7/CD44 gene signatures in GBM, we explored the HPA database for IHC to compare gene expression levels between GBM tumor tissues and normal samples." (PMID 35008426, 2022). "In the WT group, ~50% of adherent cells and 70% of suspension cells showed an average of 14–16% of partial colocalization between CD44 and CD81 on the cytoplasmic membrane, with CD81 mainly presented at the interface of the clustered tumor cells in suspension." (PMID 36193887, 2022). "In particular, a ketone derivative of THIQ (JE22) to target the CD44 HABD was synthetized and conjugated to polymeric nanoparticles via hydrazone bond to achieve a nanodevice for selective release in tumor microenvironments." (PMID 35456622, 2022). "Compared to epithelial cells (CD44 high/CD24 high), mesenchymal cells from MMTV-WNT-1(CD44 high/CD24 low) mice were tumor-initiating cells with greater tumorsphere-forming and migration abilities." (PMID 35186923, 2022). "Cleavage of the ETD of CD44 promotes tumor cell metastasis and invasion, which is regulated by the lipid modification of the CT domain and linkage of ERM or merlin with CD44 dimers." (PMID 35733341, 2022). "Although cytotoxic chemotherapy eradicates most tumor cells, CSCs are more protected and capable to recapture the heterogenic tumor mass through self-renewal with high expression of aldehyde dehydrogenase 1 A (Aldh1A), CD133, CD44 and Sox2." (PMID 35804016, 2022). "Among the membrane-associated proteoglycans, the most upregulated, including CSPG4/NG2, PTPRZ1, and CD44, function to maintain self-renewal, suppress differentiation, and assist in the migration of GBM cells, contributing to tumor invasion and recurrence." (PMID 35920986, 2022). "The synthesized HA-mPEG-Cis NPs can target CD44-positive CRC cells and dissolve the PEG hydration layer responsive to the weakly acidic tumor environment." (PMID 36033392, 2022). "We also evaluated the splenic composition of central memory T cell populations (Tcm, CD8+CD44+CD62L+) as a proxy of potential systemic memory responses against tumor antigens." (PMID 36281643, 2022). "The increased LDHB promoted more pyruvate comfort to lactic acid, and the increased lactate levels in the tumor microenvironment could promote tumor invasion and metastasis through the activation of vascular growth factor, and promotion the expression activity of hyaluronan with its receptor CD44." (PMID 35978348, 2022). "In the CD4+T cell population analyzed, PRI revealed two bin-plot patterns (CD90/CD44/CD86 and CD90/CD44/CD27) and 20 bin plot features for threshold-independent classification of mice concerning ineffective and effective tumor treatment." (PMID 35592315, 2022). "Taken together, the result indicated the involvement of TGFβ via LAP-TGFβ, cell adhesion via CD44, and extracellular matrix via FN1 in the anti-tumor action of extracellular Hsp90ab1 and MSN." (PMID 34976221, 2022). "Tumor cell-macrophage hybrids express both macrophage (CD14, CD68, CD163, CD204, and CD206) and tumor-specific markers (ALCAM, MLANA, KRT, EpCAM, CXCR4, and CD44)." (PMID 35242760, 2022). "As soon as the culture generated sufficient tumor organoids, these structures were dissociated into single cells, and FACS analyses were performed to detect the CD44+/CD24− CSC population." (PMID 35406578, 2022).
tumor (continued). "Even distantly in the inguinal lymph node, the DLN of the flank tumor, we observed a decrease in T cell priming via LFA-1+CD44+CD4 T cells in mice treated with ENI." (PMID 36385142, 2022). "Surface markers of cancer stem cells (CSCs), such as CD44 72, 73 or CD133 74, have been used in NIR-PIT to kill aggressive subpopulations of cells in the tumor, resulting in good therapeutic effects." (PMID 36276636, 2022). "By binding to transmembrane proteins (αβ integrins, CD44, EGF receptor/EGFR), MMP2 and MMP9 directly trigger intracellular signalling pathways that control tumour cell events." (PMID 35158891, 2022). "When comparing CD166 vs CD133 vs CD44 according to tumor staging, only one pattern of expression was observed in the case of CD166 and CD44 that reached the highest levels in tumor tissue at the T2 stage." (PMID 36291969, 2022). "CD44 isoforms (CD44V) play important roles in cancer, including cancer cell stemness, metastasis, and tumor initiation." (PMID 36292918, 2022). "The markers that distinguished G3 tumours from the lower grades were higher levels of synaptophysin, CD56, Ki-67, CD24, CD44, β-catenin and E-cadherin." (PMID 36362433, 2022). "Gene expression profiles of the high-risk group correlated positively with the upregulation of CSC markers, CD24, CD44, CD20, FOXM1, and EpCAM, and significant enrichment of other ESC signatures, indicating that these were tumor-promoting targets." (PMID 35814473, 2022). "CD44- and CD271-staining disclosed the intralesional presence of infiltrative tumor cell fronts and double-positive tumor cell subsets independently of the PV infection status." (PMID 35215208, 2022). "In tumor tissues, OPN, as a major chemokine, can regulate macrophage migration by interacting with integrin αVβ5, CD44, GPCR, or the CSF1–CSF1R axis." (PMID 35898884, 2022). "The results showed that CD276, CD40, CD274, CD44, and NRP1 expression was exclusively upregulated in cluster 0 (invasive tumor)." (PMID 36685583, 2022). "CSCs are a subset of tumor cells with high plasticity, which are isolated using flow cytometry with CSC markers including CD24, CD44, CD133, ALDH, and Ep-CAM." (PMID 36274852, 2022). "Accordingly, the percentage of CD44+ cells and SOX2+ cells reduced in tumor spheroids upon MEX3A knockdown, while they increased upon MEX3A overexpression." (PMID 36276637, 2022). "Evidence suggests that CD44+ TAMs can activate angiogenesis by secreting VEGFR and promote tumor cell invasion by secreting matrix metallopeptidases." (PMID 36419877, 2022). "Tumor cells in chemo-resistant samples showed higher expression of chemoresistance and proliferation related genes (FN1, LCN2, CD44, FEN1)." (PMID 36248860, 2022). "One of the more relevant actors in this scenario is the transmembrane protein CD44, which interacts with many ECM components, triggering multiple signaling cascades within tumor cells." (PMID 35785191, 2022). "This is the case for CD44, a cancer stem cell (CSC) marker involved in HNSCC tumour growth and metastasis." (PMID 35055060, 2022). "Subclusters with Entpd1 expression were assigned as tumor-specific T cells, including Treg (CD4+Foxp3+), CD8+ effector (Gzmb+Prf1+Ifng+), CD8+ effector memory (Cd44+Cd69+), CD8+ exhausted subclusters (Pdcd1+Lag3+Tigit+Havcr2+)." (PMID 36209176, 2022). "For example, within Grade 2, relative to that in the non-tumour tissue, the expression of markers CD24, CDX2, CD45 and CK6 was higher in Patient 1, and CD44 was higher in Patient 1 and Patient 3, compared to the other samples in the same group." (PMID 36362433, 2022). "CD44 is expressed on the surface of ATRT cells and tumor mesenchymal stromal cells from the rhabdoid tumor microenvironment." (PMID 35954348, 2022). "RNA-seq analysis and immunofluorescent staining of BC samples showed that the mesenchymal-like CSCs mainly express CD44+/CD24− and are primarily inactive/quiescent and localised at the edges of tumours." (PMID 36077812, 2022).
tumor (continued). "Combined use of CD44 and CD271 markers in HNSCC research recently led to the identification of CSCs as a CD271+ subpopulation within the CD44+ tumor cell compartment." (PMID 35215208, 2022). "Importantly, clinical reports indicated that CD44 expression is associated with local recurrence, regional lymph node metastasis, perineural invasion, and poorer survival rate in oral squamous cell carcinoma (OSCC), indicating its vital role in tumor recurrence and metastasis of HNSCC." (PMID 35048028, 2021). "In the three CAF isolates from HCC derived from patient 1–3 cancer stem cells (CSC) positive for CD13, CD44, CD90, CD133, OV6, epithelial cells or CSCs positive for EpCAM, or general tumor cells positive AFP were identified by immunofluorescence." (PMID 34947582, 2021). "It has been shown that CD44 and VEGF are co-expressed in cancer tissues, suggesting synergistic effects on tumor microangiogenesis and metastasis." (PMID 34932597, 2021). "It was found that the proliferation, invasion, and anti-apoptotic ability of tumor cells were significantly enhanced compared with the normoxic control group, which could promote the formation of neurospheres, increase the tumor formation rates, and upregulate CD44 and YKL40 expression." (PMID 33420370, 2021). "Sorted CD44+ OSCC cancer stem cells secrete higher levels of inflammatory cytokines and angiogenic factors than heterogeneous tumor cell population." (PMID 34205649, 2021). "With immunostaining, we confirmed the presence of CD44+ microglia (also TMEM119+) in EPN and AEP tumor sections, indicating that some CD44+ TAMs were tissue-resident microglia or their derivatives." (PMID 34824203, 2021). "Even if a universal marker for Cancer Stem Cells (CSCs) identification remains undiscovered, CSCs often express distinctive markers like CD133, CD44, ABCB1/5 (CD243), ALDH1 and many others, though many of them are tissue- and tumor-related." (PMID 34055629, 2021). "The results showed a 6-fold increase in the tumor toxicity of DOX-loaded, pH-sensitive, and CD44+-targeting NPs, as compared to free DOX." (PMID 34361141, 2021). "SYNDECAN-1, CD44, and MOESIN all have roles in cytoskeleton (such as the actin family of proteins) regulation, cell adhesion and migration and tumor tissue remodeling." (PMID 34867197, 2021). "Classical MSC markers (CD90, CD44, CD105, CD73) were also known to be expressed on cancer (stem) cells that in turn are responsible for conferring the ability of tumor regeneration." (PMID 32830458, 2021). "Cytochalasin D has been shown to block the expression of CD44, the major MMP-9 docking site on the surface of various tumor cells and primary keratinocytes." (PMID 33807594, 2021). "Immunocytochemistry further revealed co-expressions of CD44 and CD133 as well as Nestin in isolated CSCs, independently to the tumor origin." (PMID 33800955, 2021). "The expression levels of RAMP-AS1, miR-296-5p, CD44, CCND3, NCALD and MACF1 were detected in 40 tumor and adjacent tissue samples via RT-qPCR." (PMID 33281971, 2021). "We analyzed the mRNA expression of the stem cell marker, CD44, and the stem cell‐related molecule, VEGF, in the tumor tissues from two different sites, the tumor core and tumor periphery of 22 GBM patients." (PMID 33543833, 2021). "Poly6 treatment also significantly increased expression levels of CD44, indicative surface markers for activated T cells, on CD4+ and CD8+ T cells in the tumor and spleen." (PMID 33499256, 2021). "At present, numerous studies have shown that CD147 can interact with varieties of molecules to regulate the occurrence, development, invasion, and metastasis of tumor, including Annexin A2 (ANXA2), VEGFR-2, MCT1, integrin-β1, CD44, cyclophile." (PMID 35003362, 2021). "Each CD44+ cell-type functions immunosuppression through different ways: CD44+ tumor cells express CD276, IL13, VEGFA, and IDO1; CD44+ TAMs express IL10, TGFB1, VEGFA, and HAVCR2; CD44+ T cells express CD274, TGFB1, CTLA4, LAG3, and PDCD1." (PMID 35187044, 2021).